Y_RNA (Y RNA )
Gene: Miscellaneous RNA gene on chromosome 17 (36,285,312 to 36,285,413, forward strand). Ensembl gene ENSG00000265889.
Homologues: Orthologues: chimpanzee Y_RNA (96% identical), macaque Y_RNA (93% identical). Paralogues in human: Y_RNA (100% identical), Y_RNA (98% identical), Y_RNA (87% identical), RNY3 (86% identical), Y_RNA (86% identical), Y_RNA (85% identical), RNY3P1 (84% identical), Y_RNA (84% identical), Y_RNA (83% identical), RNY3P9 (82% identical), Y_RNA (82% identical), RNY3P16 (81% identical), and 95 more.